MIR7702 (microRNA 7702)
Synonyms: hsa-mir-7702
Gene: MicroRNA gene on chromosome 9 (111,271,156 to 111,271,214, reverse strand). Ensembl gene ENSG00000274263.
Homologues: Orthologues: chimpanzee MIR7702 (100% identical).